APP (amyloid beta precursor protein)
Diseases named in the same sentence as APP in open-access papers (continued):
Sharing a sentence is not in itself a finding about the gene and the disease.
Alzheimer disease (continued). "Familial forms of Alzheimer’s disease (AD) are caused by mutations in the presenilin genes or in the gene encoding for the amyloid precursor protein (APP)." (PMID 32966331, 2020). "By cleavage of APP, amyloid peptide is released and deposited as senile plaque in the brain, which is one main hallmark of the Alzheimer’s disease." (PMID 32231018, 2020). "Among these genes, APP encodes the precursor molecule of beta amyloid, the primary component of amyloid plaques found in the brains of patients with Alzheimer's disease." (PMID 31875662, 2020). "The Amyloid Precursor Protein (APP), the mutation of which can cause or prevent Alzheimer’s disease (AD), is an extensively processed type 1 transmembrane protein." (PMID 32022689, 2020). "The model carries three mutations related to familial Alzheim’s disease (FAD): APP Swedish, MAPT P301L, and PSEN1 M146 V." (PMID 31987051, 2020). "Using the progressive genetic model of Alzheimer’s disease (APP/V7171 mutation), mice on the KD had overall lower levels of amyloid-β, a neurotoxin that on accumulation forms plaques and leads to cellular death." (PMID 32680835, 2020). "APPL is an orthologue of mammalian APP (Amyloid precursor protein), which is a causative molecule of Alzheimer's disease." (PMID 31862863, 2020). "The Amyloid Precursor Protein (APP) is strongly implicated in the etiology of Alzheimer’s disease, but what is its physiological function in the adult brain?" (PMID 33290404, 2020). "The therapeutic potential of BACE1 silencing has been proposed several times due to its direct association with neurodegeneration and accumulation of APP products during early stages of Alzheimer’s disease." (PMID 32515999, 2020). "The β- and γ-secretase cleavage of amyloid precursor protein (APP) generates Aβ, which is the key component of senile plaques and, along with abnormal Aβ accumulation, represents the hallmark of Alzheimer’s disease (AD)." (PMID 32545604, 2020). "The amyloid-β precursor protein (APP) is a ubiquitous membrane protein often associated with Alzheimer’s disease (AD) and cerebral amyloid angiopathy (CAA)." (PMID 33228083, 2020). "Amyloid precursor protein (APP) is directly related to Aβ amyloidosis—a hallmark of Alzheimer’s disease (AD)." (PMID 32120908, 2020). "Our previous work reported a non canonical IRE in the 5’UTR of the Alzheimer’s disease (AD)-associated amyloid precursor protein (APP) 5’UTR." (PMID 33096655, 2020). "The most common approach to generate transgenic AD mouse models is to overexpress the Familial Alzheimer’s disease (FAD)-related human APP mutation." (PMID 33014535, 2020). "The recent identification of somatic gene recombination(SGR) in human neurons affecting the well-known Alzheimer’s disease (AD) pathogenic gene, amyloid precursor protein (APP), has implications for the normal and the diseased human brain." (PMID 32457796, 2020). "Down syndrome (DS), caused by chromosome 21 trisomy, is associated with an ultra-high risk of dementia due to Alzheimer’s disease (AD), driven by amyloid precursor protein (APP) gene triplication." (PMID 30902060, 2019). "This early-onset form of Alzheimer’s disease is rare and mutations typically found in the amyloid precursor protein (APP) and presenilin (PSEN) genes exacerbate the formation of the neurotoxic and pathologically related peptide, amyloid-β42." (PMID 31463522, 2019). "An early pathological hallmark of Alzheimer’s disease (AD) is amyloid-β (Aβ) deposits in the brain, which largely consist of up to 43 amino acids long Aβ peptides derived from the amyloid precursor protein (APP)." (PMID 30940835, 2019). "All the known mutations in genes causing early-onset Alzheimer’s disease alter amyloid precursor protein (APP) processing such that amyloid deposition becomes more likely." (PMID 32274467, 2019). "Overexpression of Aβ derived from APP is a hallmark of Alzheimer's disease and is associated with cognitive decline and neuroinflammation." (PMID 31440383, 2019).
Alzheimer disease (continued). "Alzheimer’s disease is caused by a mutation in the APP gene, or in the presenilin 1 (PSEN1) and 2 (PSEN2) genes." (PMID 29879811, 2019). "Such a model is the 5X familial Alzheimer’s disease mouse (5XFAD), which carries three disease-associated variants in APP and two disease-associated variants found in PSEN1." (PMID 30953144, 2019). "Association of memory loss with a parallel increase in the expression of APP in the brain of diabetic control mice suggests an association with Alzheimer’s disease in the diabetes model." (PMID 31068802, 2019). "As pigs are evolutionarily closer to humans, they can be used to generate transgenic pigs using a splice variant of the human APP that carries an Alzheimer’s disease-causing dominant mutation." (PMID 29879811, 2019). "Less than 1% of the AD (Alzheimer disease) cases belong to familial type due to a mutation in the APP (β-amyloid precursor protein) or PS (presenilin) 1 or PS2." (PMID 31548435, 2019). "There is a familial form of Alzheimer’s disease caused by heterozygous pathogenic variants in APP gene which encodes for amyloid precursor protein." (PMID 30871545, 2019). "For studies of Alzheimer’s Disease, transgenic mouse modelsharboring the human amyloid precursor protein (APP) and Tau mutations, which exhibitintraneuronal and extracellular amyloid pathology and Tau pathology, can be applied." (PMID 31124369, 2019). "It is due to triplication of all or part of chromosome 21, where genes, including the amyloid precursor protein (APP) gene, that play key roles in the pathogenesis of Alzheimer’s disease (AD) are encoded." (PMID 30909239, 2019). "Dysregulation of various APP trafficking components in the endosome has been previously implicated in Alzheimer’s disease (AD)." (PMID 31551717, 2019). "Presenilin 1 (PSEN1), presenilin 2 (PSEN2), and amyloid precursor protein (APP) mutations are responsible for autosomal dominant early-onset Alzheimer’s disease (AD-EOAD)." (PMID 31440394, 2019). "SORL1 processes a causal involvement in Alzheimer’s disease (AD) as a proposed modulator of the amyloid precursor protein (APP)." (PMID 31092209, 2019). "The commonest cause of progressive dementia is Alzheimer’s disease (AD), characterized by abnormal metabolism of amyloid precursor protein (APP) that leads to the formation of extracellular senile plaques made of amyloid-β (Aβ)." (PMID 31555645, 2019). "Duplication of amyloid β precursor protein (APP) gene was reported to cause autosomal dominant early-onset Alzheimer disease in five families, and various mutations in the APP gene has been identified in AD patients." (PMID 31888715, 2019). "This is associated with Alzheimer’s disease-like pathology including formation of neurofibrillary tangles, increased processing of APP as well as endosomal abnormalities." (PMID 29473871, 2018). "For example, the amyloid precursor protein (APP) has been a focus of intense investigation because of its association with Alzheimer’s disease." (PMID 29764394, 2018). "In support of this, PUM2 has been found to interact with multiple genes encoding functional proteins that are highly implicated in Alzheimer’s Disease, including amyloid precursor protein (APP), tau protein, and elF-4E." (PMID 30181804, 2018). "Impairment of γ-secretase carboxypeptidase activity, such as is caused by some familial Alzheimer’s disease mutations in APP or PSEN1 or PSEN2, can result in similar changes to the amyloid-β isoform ratios." (PMID 29945247, 2018). "APP/PS1 mice represent one of the most important animal models of Alzheimer's disease, and APP/PS1 mice show memory loss with age." (PMID 29577585, 2018). "Genetics and biochemical biomarkers currently used to identify risk factors and biomarkers of Alzheimer’s disease include APP, tau, amyloid beta 1-42, genotyping for PSEN1, PSEN2, APP, ApoE." (PMID 29868588, 2018).
Alzheimer disease (continued). "To date, about 50 pathogenic mutations of APP have been reported (Alzheimer Disease and Frontotemporal Dementia Mutation Database." (PMID 29599933, 2018). "Recently, Aβ-42, the truncated product of amyloid-precursor-protein (APP) and a causative agent for Alzheimer’s disease, has been postulated to be an AMP." (PMID 30312294, 2018). "Do the characteristics of APP’s EOfAD mutations support that APP’s role in iron homeostasis is critical for Alzheimer’s disease pathogenesis?" (PMID 30150923, 2018). "PSEN1/2 and APP gene mutations have been linked to early-onset, autosomal dominant familial forms of Alzheimer’s disease (FAD)." (PMID 30309378, 2018). "Rare early-onset familial forms of Alzheimer’s disease (AD) are associated with autosomal dominant mutations in the amyloid beta precursor protein (AβPP), presenilin 1 and presenilin 2 genes." (PMID 29520228, 2018). "Familial Alzheimer's disease (FAD): a form of Alzheimer's disease caused by mutations in a specific set of genes (APP, PSEN1 and PSEN2) that are passed down from parents to offspring in an autosomal-dominant manner." (PMID 29784664, 2018). "A recent review has noted that this pattern of clinical presentation is more similar to that seen in familial cases of Alzheimer’s disease caused by mutations in APP that decrease amyloid-β40/42 ratio, than to cases of diseases caused by duplication of APP." (PMID 29945247, 2018). "APP (amyloid precursor protein), the causative molecule of Alzheimer's disease, is synthesized in neuronal cell bodies and subsequently transported to synapses." (PMID 30226901, 2018). "Transgenic mice that overexpress APP had low leptin levels associated with hypothalamic dysfunction; low leptin levels are linked to Alzheimer’s disease." (PMID 29587359, 2018). "J20-tgAPP mice overexpress a human APP transgene with Alzheimer’s disease mutations and accumulates amyloid-β within the brain from ∼4–5 months of age." (PMID 29945247, 2018). "Initially, the overexpression of APP, a HSA21 gene encoding the amyloid precursor protein (APP) was thought to confer a higher risk of early onset of Alzheimer’s Disease to patients with DS." (PMID 30332747, 2018). "The most severe EOfAD mutations in APP (those with the earliest Alzheimer’s disease onset ages) affect the transmembrane domain amino acid residues critical for dimerization." (PMID 30150923, 2018). "In human neuronal models of monogenic Alzheimer’s disease, APP and PSEN1 mutations disrupt lysosome function and autophagy, leading to impaired lysosomal proteolysis and defective autophagosome clearance." (PMID 30590039, 2018). "APP (amyloid precursor protein) is one of the causative genes of the familial type of Alzheimer's disease." (PMID 30226901, 2018). "The extra copy of APP, encoded on chromosome 21, has a central role in Down syndrome-Alzheimer’s disease pathogenesis." (PMID 29945247, 2018). "Individuals with DS are at increased risk of developing Alzheimer’s disease as a result of triplication of the amyloid precursor protein (APP) gene." (PMID 29342922, 2018). "Conversely, a mutation in the APP gene has been identified that decreases APP production and provides a protective effect against development of Alzheimer’s disease." (PMID 30509933, 2018). "In Alzheimer’s disease (AD), levels and aggregation of the causative amyloid-β (Aβ) are affected by aberrant proteolytic cleavage of the amyloid precursor protein (APP)." (PMID 29780404, 2018). "The central pathogenic event in Alzheimer’s disease (AD), the most common cause of dementia, is the deposition of amyloid β (Aβ), a truncated fragment of the amyloid precursor protein (APP), which leads to the formation of extracellular Aβ plaques." (PMID 29310723, 2018). "One of the major substrates of Adam10 is amyloid precursor protein (APP), for which Adam10 acts as an α-secretase to prevent the excessive production of the pathogenic amyloid β (Aβ) peptide, a hallmark of Alzheimer’s disease (AD)." (PMID 30075790, 2018).
Alzheimer disease (continued). "Accumulating evidence has demonstrated that exosomes are associated with amyloid precursor (APP) and Tau proteins and play a controversial role in Alzheimer’s disease process." (PMID 28184302, 2017). "For example, in Alzheimer's disease, we noted that all associated genes (APP, PSEN1, and PSEN2) were reported to show an increase in Aβ in neurons (Fig EV3A)." (PMID 29051230, 2017). "The only gene indirectly linked to oocyte maturation was APP, responsible for amyloid plaques formation in the brain of patients with Alzheimer’s disease." (PMID 29232894, 2017). "The J20 mouse model of Alzheimer’s disease (AD) is a transgenic overexpresser of human APP with familial AD mutations and has been extensively utilised in preclinical studies and our aim was to determine the genomic location of the J20 transgene insertion." (PMID 29062914, 2017). "Amyloidogenic processing of APP by β- and γ-secretases leads to the generation of amyloid-β peptide (Aβ), and the accumulation of Aβ in senile plaques is a hallmark of Alzheimer’s disease (AD)." (PMID 29245900, 2017). "While APP has been studied extensively as the precursor of amyloid beta (Aβ) peptides implicated in the pathogenesis of Alzheimer's disease (AD), the physiological functions of APP have yet to be fully elucidated." (PMID 28537903, 2017). "Physiological function and pathology of the Alzheimer’s disease causing amyloid precursor protein (APP) are correlated with its cytosolic adaptor Fe65 encompassing a WW and two phosphotyrosine-binding domains (PTBs)." (PMID 28553201, 2017). "Gradual accumulation of β-amyloid peptide (Aβ), the proteolitic product of amyloid precursor protein (APP), is the principal cause of synaptic dysfunction and cognitive loss in Alzheimer disease." (PMID 29435372, 2017). "It is of note that the APP gene, which encodes the amyloid beta precursor protein, predisposes to dominant forms of Alzheimer’s disease (AD) but also harbours rare variants with a protective effect on AD12." (PMID 28428554, 2017). "A hallmark of Alzheimer’s disease is senile plaques composed of amyloid beta (Aβ) protein derived from the amyloid precursor protein (APP)." (PMID 29267198, 2017). "Amyloidogenic processing of APP by β- and γ-secretases leads to the generation of amyloid-β peptide (Aβ), and accumulation of Aβ to form senile plaques is a hallmark of Alzheimer’s disease (AD)." (PMID 29245900, 2017). "APP is a key protein associated with Alzheimer’s disease and is involved in the migration of neuronal precursor cells." (PMID 26803493, 2017). "Olfaction is often deregulated in Alzheimer’s disease (AD) patients, and is also impaired in transgenic Tg2576 AD mice, which overexpress the Swedish mutated form of human amyloid precursor protein (APP)." (PMID 29077059, 2017). "Abnormal metabolism of APP results in β-amyloid accumulation, causing neuronal degeneration in the brains of AD (Alzheimer's disease) patients." (PMID 28212331, 2017). "There are two different form of Alzheimer’s disease: the hereditary “familial” form is characterized by an early onset (before age 50) associated with mutations in the APP gene and the genes for PS1 or PS2." (PMID 29068387, 2017). "Altered processing of the Amyloid Precursor Protein (APP) is a well-recognized central pathogenic mechanism in Alzheimer's Disease (AD), and regulation of APP processing is a major focus of research in the AD field." (PMID 29163761, 2017). "Activation of 5‐HT4d has been shown to modulate α‐secretase activity, thus promoting the generation of the amyloid precursor protein (APP)α at the expense of the Alzheimer disease‐associated APPβ." (PMID 28298427, 2017). "APP mutations cause Alzheimer’s disease, and over-expression of APP has a link with shortened survival in patients with breast cancer." (PMID 28924174, 2017). "The pathogenesis of Alzheimer's disease (AD) is linked to the proteolytic processing of the amyloid precursor protein (APP) to the amyloidogenic peptide Aβ." (PMID 29163761, 2017).
Alzheimer disease (continued). "There was a consistent increase in the abundance of mRNA encoding Alzheimer’s disease amyloid precursor protein (APP) in T/T mice in both arrays." (PMID 26803493, 2017). "Research into the causes and progression pathways of Alzheimer disease (AD) has focussed primarily on the roles of the amyloid beta protein (Aβ) derived from the amyloid precursor protein (APP) via sequential proteolytic cleavages." (PMID 28126004, 2017). "It was also projected the genetic cause of Alzheimer disease (AD) is understood for less than 1% gene mutations (APP, PS1, PS2) in early onset FAD or 20% (APOE4 allele) in late onset FAD cases, respectively." (PMID 28072821, 2017). "Familial Alzheimer’s disease (AD) is caused by mutations in the genes that encode amyloid precursor protein (APP) and presenilins." (PMID 29109429, 2017). "We recruited 48 individuals from families with PSEN1 or APP mutations to a cross-sectional study: 18 had symptomatic Alzheimer disease (AD) and 30 were asymptomatic but at 50% risk of carrying a mutation." (PMID 29070659, 2017). "The amyloid precursor protein (APP) is a type I transmembrane protein that has first been identified related in association with Alzheimer's disease (AD) as representing the precursor of amyloid β (Aβ) peptides." (PMID 28496400, 2017). "Amyloid-β (Aβ) precursor protein (APP) and metabolites are usually associated with Alzheimer’s disease (AD)." (PMID 27212113, 2016). "Mitochondrial dysfunction has been linked to the pathogenesis of Alzheimer ́s disease and both Aβ and APP have been reported to affect mitochondrial function in isolated systems." (PMID 28005987, 2016). "Alzheimer’s disease is believed to be driven by the accumulation and deposition of the amyloid beta precursor protein that encoded by APP in brain region." (PMID 26833210, 2016). "β-Amyloid precursor protein (APP) and its cleaved products are strongly implicated in Alzheimer's disease (AD)." (PMID 26194181, 2016). "So far, several genes have been associated with Alzheimer’s disease in DS patients, such as APP, BACE2 and PICALM." (PMID 27266699, 2016). "Many studies have underlined striking analogies between PMEL and APP that forms pathological amyloids involved in Alzheimer’s disease." (PMID 27589732, 2016). "Previous studies have linked several naturally occurring mutations in the gene encoding APP to inherited forms of Alzheimer’s disease." (PMID 27580372, 2016). "Alzheimer's disease (Tg2576) and Down syndrome (Ts65Dn) mice, which overexpress human and mouse APP respectively, are highly susceptible to AGS." (PMID 28018172, 2016). "Here we show that the Amyloid Precursor Protein (APP), a central molecule in Alzheimer’s disease, associates with the PIKfyve complex (consisting of Vac14, PIKfyve and Fig4) and that the APP intracellular domain directly binds purified Vac14." (PMID 26216398, 2016). "The hnRNP C is linked to Alzheimer’s disease (AD) characterized by amyloid-b plaques formed by the amyloid-beta protein, which is a cleavage product of APP." (PMID 27215579, 2016). "The amyloid precursor protein (APP) is a causal agent in the pathogenesis of Alzheimer’s disease and is a transmembrane protein that associates with membrane-limited organelles." (PMID 26814888, 2016). "Aβ is derived by proteolytic processing from the amyloid precursor protein (APP) and mutations in APP are causative for some dominantly inherited forms of Alzheimer's disease." (PMID 26899735, 2016). "DISC1 also directly affects C-terminal processing of APP and generation of the β-amyloid (Aβ) peptide, a pathological hallmark of Alzheimer’s disease (AD)." (PMID 27370822, 2016). "Depiction of the mechanism underlying β-escin influence on APP processing and the potential role of the drug in prevention and/or therapy of Alzheimer's disease merits more thorough studies." (PMID 27727329, 2016).